CD36 (CD36 molecule (CD36 blood group))
Diseases named in the same sentence as CD36 in open-access papers (continued):
Sharing a sentence is not in itself a finding about the gene and the disease.
Stroke (continued). "A previous study reported that CD36 can negatively regulate TLR2 expression following adult stroke." (PMID 32903800, 2020). "Indeed, CD36 signaling is induced after cerebral stroke and plays a pivotal role in stroke-induced inflammation." (PMID 29202856, 2017). "Cd36 inhibition was suggested as a viable strategy to enhance possible recovery in stroke." (PMID 23951329, 2013). "However, the pharmacological inhibition of CD36 in hyperlipidemic stroke worsens the outcome." (PMID 32174916, 2020). "Using qRT‐PCR assays, we detected elevated mRNA expression of FA transporter CD36 and key mediators in FA β‐oxidation, including CPT1α, PPARα and ACOX1, confirming a hepatic shift towards enhanced FAO following stroke." (PMID 38666466, 2024). "For example, CD36 has been linked to cardiovascular diseases including stroke or chronic ischemia and cerebral microhemorrhages caused by ministrokes could contribute to the development of a DAT67, thus potentially mediating the effect of CD36 polymorphisms on AD." (PMID 35768560, 2022). "Knowing that TLR4 is one of common CD36 co-receptor partners during inflammation and cerebral ischemia, including neonatal stroke, we measured protein levels of TLR4 in the ipsilateral and contralateral CPs of WT and CD36 KO mice." (PMID 35148760, 2022). "The class B scavenger receptor CD36, which is primarily found in microglia and macrophages, is co-located with GFAP in the peri-infarct astrocytes at 3–7 days after stroke." (PMID 32174916, 2020). "We detected a significant reduction in PPARγ DNA-binding activity in the brain tissue and mRNA levels of BBB junctional proteins and PPARγ-targeting gene CD36 and FABP4 in cerebral microvasculature at 24 h after stroke." (PMID 32012810, 2020). "WT, NLRP3-/-, CD36-/-, and OPN-/- mice underwent DH stroke and were killed 24 h later for determination of acute infarct size." (PMID 30417081, 2018). "We then performed immunohistochemistry for CD36 and MBP, revealing that, although many MBP+ cells disappeared from the ischemic areas, MBP+ staining, which did not keep the original arrangement, was observed in ischemic areas even after stroke." (PMID 39451255, 2024). "However, in this study the genetic ablation of CD36 had little impact on chronic cytokine production and MMP expression after stroke." (PMID 30417081, 2018). "Congruently, we have previously shown that infarct size following the intraluminal filament MCAO model of stroke is equivalent in OPN-/- and WT mice, however, NLRP3-/- and CD36-/- mice have been reported to have smaller infarct volumes compared to WT mice following intraluminal filament MCAO." (PMID 30417081, 2018). "Interestingly, only preventative, but not post-stroke inhibition of CD36 attenuated brain swelling in hyperlipidemic stroke." (PMID 35148760, 2022). "In summary, we report that HIF-1α in microglia after stroke may facilitate phagocytosis and other microglial functions including chemotaxis, ROS production, and TNF-ɑ production through CD36 and/or MFG-E8 hence interfering with adult neurogenesis in the acute phase of ischemic stroke." (PMID 29340071, 2017). "Interestingly, the role of CD36 in the resolution of neuroinflammation in different noninfectious models has been previously reported, such as in Alzheimer’s disease, stroke, ischemic brain due to middle cerebral artery occlusion, brain hematoma, or germinal matrix hemorrhage." (PMID 36310859, 2022). "This hypothesis is supported by a study demonstrating an increase in the extent of injury in mice lacking CD36 after acute neonatal stroke and on the other hand by a study in which genetic deletion of CD36 provided benefit in a transient model of ischemic stroke." (PMID 29202856, 2017). "Stroke induced an increase in MCP-1 at 6 h and 72 h after ischemia in the diabetic peritoneal cells, while IL-6, CCR2, and CD36 gene expressions were not different between the normal and diabetic cells." (PMID 24886035, 2014).
nonalcoholic fatty liver disease (35 papers, 2014 to 2025). "Several studies demonstrate that an increased hepatic CD36 expression is associated with enhanced susceptibility to nonalcoholic fatty liver disease." (PMID 27806127, 2016). "A soluble form of CD36 (sCD36) has previously been demonstrated to be present in circulation, and increased levels have been associated with abdominal fat distribution, insulin resistance, and non-alcoholic fatty liver disease (NAFLD)." (PMID 30386406, 2018). "In non-alcoholic fatty liver disease, CD36 influences lipogenesis via SREBP1 processing, which is also elevated in lipopolysaccharide-induced M1 macrophages." (PMID 41011253, 2025). "By influencing lipid metabolism, CD36 can accelerate the development of chronic inflammation and fibrosis in nonalcoholic fatty liver disease; microRNA-29 can halt these effects by suppressing the expression of CD36." (PMID 37593175, 2023). "Studies have shown that inhibition of CD36 palmitoylation can promote the localization of CD36 to hepatocyte mitochondria to alleviate nonalcoholic fatty liver disease." (PMID 36611964, 2022). "CD36 is a central regulator in the development of nonalcoholic fatty liver disease, and meanwhile, it plays an important role in the progression of liver cancer." (PMID 36406414, 2022). "A recent study has demonstrated that in non-alcoholic fatty liver disease, inhibition of CD36 palmitoyl modification increases mitochondrial FAO by activating AMPK, which reduces inflammation in the liver tissue." (PMID 34021126, 2021). "Fatty acid translocase CD36 (CD36) plays an important role in the initiation and pathogenesis of chronic liver disease and non-alcoholic fatty liver disease (NAFLD)." (PMID 33344451, 2020). "There are some findings presenting that fatty acid translocase (FAT/CD36) expression, which is important fatty acid transporter, is increased in patients with nonalcoholic fatty liver disease and CD36 is involved in increased FFA uptake." (PMID 25635851, 2015). "Furthermore, sweroside improves nonalcoholic fatty liver disease in mice by modulating the expression of the Cd36 and Fgf21 genes, thereby impacting lipid metabolism and the inflammatory response." (PMID 41282626, 2025). "Furthermore, according to a previous study, increased mitochondrial CD36 expression leads to more acyl-CoA oxidation by mitochondria in hepatocytes, which contributes to the reduction of lipid accumulation in non-alcoholic fatty liver disease." (PMID 36677577, 2023). "Downregulation of miR-20a-5p is accompanied by upregulation of one of its targets, CD36 (CD36 molecule), and increased lipid deposition, suggesting novel pathogenesis of non-alcoholic fatty liver disease and a potential therapeutic strategy for metabolic diseases." (PMID 36230953, 2022). "Interestingly, by targeting liver HSC cells in nonalcoholic fatty liver disease, previous studies suggested that CD36 is related to liver cirrhosis and might promote fibrosis." (PMID 37593175, 2023). "CD36 levels are higher in patients with nonalcoholic fatty liver disease (NAFLD), possibly leading to the development of nonalcoholic steatohepatitis." (PMID 39608717, 2024). "Through the CD36-PPAR-CYP4A3 pathway, our work showed that large doses of icariin can greatly reduce lipid buildup in the liver and increase mitochondrial fatty acid oxidation in the liver, further reducing non-alcoholic fatty liver disease." (PMID 36677577, 2023). "Cd36, Cidea, and Fabp1 are considered PPARA-dependent genes that are highly expressed under metabolic stress in liver and could be potential therapeutic targets for nonalcoholic fatty liver disease." (PMID 38786053, 2024).
Hypertension (31 papers, 2005 to 2026). The presence of chronic increased pressure in the systemic arterial system. "For instance, an association between the CD36 rs1761667 polymorphism and susceptibility to hypertension has been highlighted." (PMID 40565543, 2025). "Conversely, it has been suggested that the AA genotype of rs1761667 in the CD36 gene is associated with a lower risk of hypertension in a Japanese population." (PMID 38674354, 2024). "A correlation between the CD36 rs1761667 polymorphism and susceptibility to hypertension has been demonstrated in the Iranian population." (PMID 38674354, 2024). "The association of CD36 rs1761667 with BMI and hypertension has also been studied in a cohort of adults, showing a correlation between the AA genotype and lower BMI as compared to AG and GG." (PMID 37960309, 2023). "Contrary to the previous studies, our CAD subjects as well as those with a combination of CAD and hypertension showed a lower risk in A allele carriers of CD36 rs1761667 SNP." (PMID 31185924, 2019). "The present findings revealed an association between CD36 rs1761667 polymorphism and susceptibility to hypertension and/or CAD in a southeastern Iranian population." (PMID 31185924, 2019). "The present study was conducted to investigate the possible association of CD36 rs1761667 (G > A) polymorphism with hypertension and/or CAD in the southeastern of Iran." (PMID 31185924, 2019). "Recently, evidence of the implication of only one renal gene (Cd36) predisposing to hypertension in SHR was clearly demonstrated." (PMID 22272763, 2012). "These issues have only recently been resolved by implicating Cd36 as a determinant of blood pressure and risk for hypertension by specifically identifying deficient renal expression of Cd36." (PMID 20035862, 2010). "In a similar context, there is a suggestive hypothesis that a decrease in CD36 expression in renal cells could be linked to hypertension." (PMID 38674354, 2024). "In addition, CD36/FAT degradation interrupts the cellular transport of long-chain fatty acids in patients with hypertension and genetic variants of rs10009742." (PMID 36422279, 2022). "Since reducing nitric oxide activity in the renal medulla is associated with hypertension, it is proposed that a decreased CD36 in renal cells may be related to hypertension." (PMID 35396566, 2022). "Next, we examined whether Ang II-induced hypertension increases expression of scavenger receptors (CD36) associated with the ability to uptake lipids (OxLDL) in macrophages." (PMID 34572127, 2021). "The present study presented the first evidence which suggests that CD36 rs1761667 gene polymorphism might be a factor predisposing to hypertension and CAD in a southeastern Iranian population." (PMID 31185924, 2019). "Furthermore, using a recessive inheritance model CD36 rs1761667 polymorphism was significantly associated with an increased risk of CAD with hypertension (OR = 5.677; 95% CI = 1.053–30.601; p = 0.043)." (PMID 31185924, 2019). "Decreased NO activity in renal medulla is found to be associated with hypertension, suggesting that reduced CD36 in renal cells may be associated with hypertension." (PMID 31185924, 2019). "The +273A/G polymorphism in CD36 was associated with essential hypertension especially in males." (PMID 28804718, 2017). "One study suggested that the onset of myocardial metabolic disorders during the early stage of hypertension decreased plasma CD36/FAT content and function, leading to decreased FA transport capacity." (PMID 36422279, 2022). "Association between CD36 rs1761667 genotypes and the risk of CAD and hypertension was assessed using multinomial regression by adjusting for age, sex, creatinine, fasting blood sugar (FBS), systolic blood pressure (SBP) and diastolic blood pressure (DBP)." (PMID 31185924, 2019).
Hypertension (continued). "It is noteworthy that even though the role of CD36 in multiple diseases has been revealed, it is the first study which sought to examine the genetic variation of CD36 in association with CAD and/or hypertension susceptibility." (PMID 31185924, 2019). "It is known that hypertension plays an important role in the pathogenesis of ICH, and many studies have found that CD36 is closely related to the development of hypertension." (PMID 28804718, 2017). "Hypertension may also affect FA transport via a cluster of differentiation 36/fatty acid translocase (CD36/FAT)." (PMID 36422279, 2022). "Therefore, the present study assessed the association of CD36 rs1761667 gene polymorphism with susceptibility to CAD and/ or hypertension on an Iranian southeastern population." (PMID 31185924, 2019). "Therefore, the present study was conducted aiming to evaluate the CD36 rs1761667 polymorphism in patients with CAD and hypertension in a southeastern Iranian population." (PMID 31185924, 2019). "The crucial role that CD36 plays in hypertension has been revealed by molecular studies." (PMID 31185924, 2019). "In our study, the results showed that rs1194182 polymorphism in the CD36 was significantly associated with ICH in the hypertension group, which indicated that significant correlation existed between rs1194182 polymorphism and hypertension on ICH." (PMID 28804718, 2017). "Furthermore, by conserved genome analysis, a data set of 73 candidate genes for hypertension, including Cd36 and Gstm1, have been identified that merit translational studies in human populations." (PMID 20035862, 2010). "Differentially expressed PNMT, MPZ, RAB3C, and CD36 can be potential targets for AMH, providing a theoretical basis for mechanistic exploration of AMH along with hypertension." (PMID 36583008, 2022). "It has been confirmed that (P)RR can promote the expression of downstream proteins related to fatty acid synthesis and transport, such as ACC-1, FAS, and CD36, by upregulating the expression of ERK/PPARγ, thereby inducing the occurrence of hypertension combined with MAFLD." (PMID 40650317, 2025). "Of note, PNMT, MPZ, RAB3C, and CD36 are found to differentially expressed and can be potential targets for AMH, providing a theoretical basis for mechanistic exploration of AMH along with hypertension." (PMID 36583008, 2022). "Subgroup analysis conducted for the SNP rs1194182 in CD36 showed that GG genotype frequencies were significantly different between ICH patients and controls in hypertension group via a dominant model, especially in the hypertension group." (PMID 28804718, 2017). "It is known that these rats have a defect in CD36, which leads to defects in fatty acid metabolism but does not affect the hypertension, but the exact impact this reduction in CD36 has on respiratory function is not yet known." (PMID 19930705, 2009). "Importantly, biopsy samples from cases of FSGS that were matched for degree of proteinuria, renal function, and hypertension were characterized by TED, IF, and increased tubular epithelial apoptosis; however, proximal tubular CD36 expression was similar to that in normal human control kidney." (PMID 15737001, 2005).
cerebral malaria (30 papers, 2006 to 2024). A sequestration of Plasmodium falciparum in the brain, which can cause coma and/or seizures. "A single human genetics study on CD36 polymorphisms in South East Asia (SEA) reported that CD36 deficiency was protective against cerebral malaria." (PMID 28249043, 2017). "Although the study only shows data for CD36, further studies should address the possibility of a similar effect on receptors implicated in cerebral malaria such as CD54 and endothelial protein C receptor." (PMID 28486940, 2017). "In two cerebral malaria patients, the transcript profile was dominated by transcripts encoding proteins predicted to bind CD36 (patients 1996, 1995)." (PMID 27354391, 2016). "Likewise, the positive correlation between the high transcription level of group B var genes and the increased binding of isolates from CM patients strengthens the implication of group B var encoding PfEMP-1 in the binding interaction with CD36 during cerebral malaria." (PMID 25156105, 2014). "Therefore, the correlation among transcription patterns of group B variants, which are characterized by CIDR and DBL domains, binding phenotype to CD36, and severity of the disease reflects the existence of conserved phenotypes associated with cerebral malaria." (PMID 25156105, 2014). "Malian children with cerebral malaria lack antibodies to both CD36 and non-CD36 binding PfEMP1 fragments compared to uncomplicated malaria." (PMID 36419237, 2023). "Rosiglitazone increases CD36-mediated phagocytosis of infected erythrocytes, has anti-inflammatory properties and improved survival in a cerebral malaria model previously." (PMID 27905921, 2016). "Association results for cerebral malaria risk single-nucleotide polymorphisms (SNPs) genotyped in TGFB2, CD36, HBB and HMOX1 genes." (PMID 20585394, 2010). "Another adhesion molecule that is likely involved in cerebral malaria pathogenesis is CD36, a receptor with a wide tissue distribution that is also found on endothelial cells." (PMID 19680452, 2009). "The exclusive expression of CD36 in haematopoietic cells resulted in 25% protection from experimental cerebral malaria (ECM)." (PMID 17367535, 2007). "Nevertheless, it is possible that CD36 heterozygosity at rs3211938 interferes with the adhesion of IE to endothelial cells, a proposed cerebral malaria pathogenesis mechanism that involves other surface molecules expressed in endothelial cells, including ICAM-1, PECAM-1 and EPCR." (PMID 31417551, 2019). "In addition, peroxisomal proliferator associated receptor-γ (PPAR-γ) mediated differentiation of monocytes towards a less inflammatory status is accompanied by up-regulation of CD36, which has been used to clinical advantage in cerebral malaria." (PMID 18554409, 2008). "The increase in CD36 may be relevant to the pathogenesis of behavioral abnormalities and pathology given its role in other conditions including cerebral malaria and Alzheimer's disease." (PMID 18947414, 2008). "Could other receptors like CD36 be involved in cerebral malaria too?" (PMID 28646215, 2017). "Thus, the role of CD36 adhesion in cerebral malaria remains unclear." (PMID 36419237, 2023). "Nevertheless, the cytoadhesion predictions for CD36, EPCR, and ICAM-1 are supported by multiple in vitro studies of both laboratory-adapted P. falciparum lines (21, –, 23, 26, –, 28) and cerebral malaria isolates." (PMID 31040236, 2019). "Almost all patient isolates bind to CD36, while the binding to ICAM-1 has widely different avidities among clinical isolates and is common among African patients with highest binding in cerebral malaria." (PMID 19650937, 2009). "A significant proportion of chimeric mice expressing CD36 only in haematopoietic cells did not die from cerebral malaria." (PMID 17367535, 2007). "All mice reconstituted with syngeneic bone marrow cells as well as chimeric mice expressing CD36 exclusively in non-haematopoietic cells died from experimental cerebral malaria between day 6 and 12 after infection." (PMID 17367535, 2007).
cerebral malaria (continued). "Moreover, recent experiments with mice deficient in CD36, indicate that this receptor is involved in the sequestration of Plasmodium berghei ANKA to the lung and adipose tissues but not in the development of cerebral malaria." (PMID 16914051, 2006).